ATAD2 (ATPase family AAA domain containing 2)
Diseases named in the same sentence as ATAD2 in open-access papers (continued):
Sharing a sentence is not in itself a finding about the gene and the disease.
lung carcinoma (15 papers, 2014 to 2025). "Loss of ATAD2 reduced lung cancer cell viability and proliferation." (PMID 35672694, 2022). "This study confirmed that IH regulates the interaction between mtROS and CSCs by mediating HIF-1α/ATAD2, promoting lung cancer progression." (PMID 38605948, 2024). "ATAD2 knockdown inhibited the migration, invasion, stem cell-like properties, and mitochondrial reactive oxygen species (mtROS) production of lung cancer cells." (PMID 36008934, 2022). "Hsa-miR-372 is already a potential marker of lung cancer, and regulates an ATPase family member ATAD2, a translocase of inner mitochondrial membrane 17 (TIMM17A) and the transcription factor E2F5." (PMID 24866763, 2014). "Knockdown of ATAD2 significantly inhibited the invasion and migration of lung carcinoma cells." (PMID 38605948, 2024). "Recent studies suggest intermittent hypoxia may interfere with mtROS in lung cancer cells to play a carcinogenic role through the HIF-1 α/ATAD2 pathway." (PMID 37842058, 2023). "The present study also suggests a novel mechanism by which the integrity of CIH-triggered HIF-1α/ATAD2 may determine lung cancer aggressiveness via the interplay of mtROS and stemness in lung cancer cells." (PMID 35672694, 2022). "ATAD2 overexpression was a poor prognostic factor for lung cancer patients." (PMID 35672694, 2022). "Additionally, ATAD2 knockdown repressed lung cancer cell migration, invasion, stem-cell-like properties, and mtROS production." (PMID 35672694, 2022). "ATAD2 has been reported to be highly expressed in a variety of human malignancies, including gastrointestinal malignancies, reproductive malignancies, urological malignancies, lung cancer, and other types of malignancies." (PMID 36008934, 2022). "In addition, ATAD2 also promotes the proliferation, tumorigenicity, and migration of lung cancer cells utilizing the PI3K/AKT pathway." (PMID 36008934, 2022). "In lung cancer, HIF-1α activates ATAD2 to enhance cancer development, which may further facilitate mitochondrial ROS production that contributes to enhancing cancer cell stemness." (PMID 36632213, 2023). "The integrity of HIF-1α/ATAD2 triggered by CIH may determine the aggressiveness of lung cancer through the interaction of mtROS and stemness in lung cancer cells." (PMID 36008934, 2022). "In order to confirm the expression of ATAD2 in various tumors, we performed immunohistochemistry analysis on tissue microarrays (TMA) from multiple cancer types including breast, prostate, gastric, colorectal and lung cancers." (PMID 27612420, 2016). "Knockdown of ATAD2 inhibited lung cancer cell invasion and migration, reduced mtROS production, and decreased both the quantity and functional capacity of CSCs, suggesting that IH accelerates lung cancer progression by activating the HIF-1α/ATAD2 axis, regulating mtROS and CSC interactions." (PMID 41194928, 2025).
prostate carcinoma (15 papers, 2013 to 2025). A carcinoma that arises from epithelial cells of the prostate gland. "The expression of ATAD2 in human prostate surgical specimens was detected by immunohistochemistry and its outcome revealed that ATAD2 overexpression in prostate cancer was associated with disease progression." (PMID 36008934, 2022). "For example, a neighboring gene, ATAD2, has been found to be a co-regulator of MYC and overexpression of ATAD2 has been associated with poor prognosis in breast, lung, and prostate cancers." (PMID 23393560, 2013). "High expression of ATAD2 has previously been found to be associated with an unfavorable prognosis in breast, lung, and prostate cancers and it has been suggested that ATAD2 contributes to the development of aggressive cancer through linking of the E2F and MYC pathways." (PMID 23393560, 2013). "ATAD2 is expressed in androgen-dependent and androgen-sensitive prostate cancer (PC) cells in response to androgen stimulation, and its levels are further elevated in androgen-independent and hormone-refractory PC cells." (PMID 41154392, 2025). "It has been found that inhibition of ATAD2 strongly impedes the proliferation of prostate cancer cells and leads to apoptosis enhancement." (PMID 36632213, 2023). "For instance, in prostate cancer LNCaP cells, ATAD2 affects the recruitment of histone methylase mixed lineage protein-1 (MLL1) and RNA polymerase II during enhancer of zeste homologue 2 (EZH2) gene transcription." (PMID 36632213, 2023). "For instance, KDM8 / JMJD5, a histone lysine demethylase/dioxygenase, directly targets ATAD2 to maintain cell survival via AR activation of EZH2 in prostate cancer." (PMID 36632213, 2023). "In prostate cancer, ATAD2 can bind to the promoter of EZH2 together with KDM8 and E2F1 to promote the transcription of EZH2." (PMID 36632213, 2023). "The upregulation of NSD2 expression acts as a key function for prostate cancer cell proliferation, survival, and tumor angiogenesis, and ATAD2 acts as an AR co-activator that enhances its transcriptional activity." (PMID 36008934, 2022). "ATAD2 also shows a high expression in numerous prostate cancer subtypes." (PMID 36008934, 2022). "Also in prostate cancer E2F1 binds the ATAD2 gene regulatory region to activate its gene transcription." (PMID 26308378, 2015). "ATAD2 is within a commonly amplified region (8q24) across multiple cancer types and its expression seems to be a predictor of poor prognosis in BC and in other tumors, as in prostate cancer." (PMID 24866763, 2014). "In prostate cancer cells, testosterone induces the expression of both EZH2 and ATAD2." (PMID 41154392, 2025). "The expression inhibition of ATAD2 intensely suppressed androgen-responsive or non-androgen-dependent AR-positive prostate cancer cell proliferation and led to a significant rise in tumor cell apoptosis." (PMID 36008934, 2022).
gastric cancer (13 papers, 2016 to 2025). A primary or metastatic malignant neoplasm involving the stomach. "Significant gains of genes ATAD2, DSCC1, FAM91A1, and MYC brought to the enrichment of the Gastric Cancer Network 2 pathway, and ATAD2 is a cancer-associated protein which can also induce the expression of Cyclin D1 and MYC." (PMID 31921654, 2019). "In gastric cancer, the downregulation of miR-520f that targets ATAD2 resulted in increased ATAD2 expression and, hence, increased cell proliferation." (PMID 41154392, 2025). "We found it particularly interesting that in stomach cancer cells, ATAD2 is upregulated during hypoxia in a Hif1α-dependent manner and promotes cell proliferation." (PMID 40962957, 2025). "And silencing ATAD2 inhibits the proliferation of gastric cancer cells by reducing the expression of the key cell cycle regulator proteins cyclin D1, Rb, E2F1 and cyclin E, thereby arresting the cell cycle in the G1/S phase 40." (PMID 36632213, 2023). "Like gastric cancer, ATAD2 also promotes the proliferation of CRC cells through the pRb-E2F1 pathway." (PMID 36008934, 2022). "For example, miRNA-520f reduces the expression of ATAD2 to inhibit the proliferation of gastric carcinoma cells." (PMID 36139505, 2022). "Similar results have also been found in other ATAD2-related studies, such as those on colorectal cancer, gastric cancer, and cervical cancer, in which overexpressed ATAD2 levels often existed in more aggressive tumor subgroups." (PMID 32462022, 2020). "Insight into the ATAD2–PPI interface provides a new target for gastric cancer therapy." (PMID 36008934, 2022).
ovarian carcinoma (12 papers, 2013 to 2024). A malignant neoplasm originating from the surface ovarian epithelium. "We identified epigenetic regulator ATPase family AAA domain-containing 2 (ATAD2) is overexpressed in ovarian cancer and is associated with increased incidences of metastasis and recurrence." (PMID 37479754, 2023). "Our analysis of other publicly available ovarian cancer data sets revealed that ATAD2 mRNA expression was higher in metastatic and high-grade ovarian cancer samples and was associated with increased incidence of recurrence in patients." (PMID 37479754, 2023). "To gain mechanistic insight regarding how ATAD2 inhibition results in cell-cycle arrest and apoptosis induction, we analyzed RNA sequencing data to identify the genes associated with cell-cycle functions that are altered in ovarian cancer cells following BAY-850 treatment." (PMID 37479754, 2023). "MiR-200b-5p inhibits ovarian cancer cell proliferation and promotes apoptosis by targeting ATAD2 and regulating the PI3K/AKT signaling pathway." (PMID 36632213, 2023). "In our study, we show that ATAD2 is overexpressed and promotes tumor growth and metastasis in ovarian cancer models." (PMID 37479754, 2023). "In this study, we found that ATAD2 inhibition suppressed the tumor growth and metastasis of ovarian cancer cells." (PMID 37479754, 2023). "Transcriptome-wide mRNA expression profiling of ovarian cancer cells treated with BAY-850 revealed that ATAD2 inhibition predominantly alters the expression of centromere regulatory genes, particularly centromere protein E (CENPE)." (PMID 37479754, 2023). "Recently, a study found that the transcription factor MYBL2 can bind to the promoter of ATAD2 to promote the expression of ATAD2 to trigger ovarian cancer cell proliferation." (PMID 36632213, 2023). "To understand the role of ATAD2 in ovarian cancer, we first analyzed ATAD2 mRNA expression levels in ovarian cancer patient samples." (PMID 37479754, 2023). "Genetic knockdown of ATAD2 or its pharmacological inhibition via ATAD2 inhibitor BAY-850 suppressed ovarian cancer growth and metastasis in both in vitro and in vivo models." (PMID 37479754, 2023). "To further support our findings, we used two sequence-independent short hairpin RNA (shRNA) constructs to genetically knock down ATAD2 expression and examined the effect of ATAD2 knockdown on ovarian cancer growth using the soft-agar assay." (PMID 37479754, 2023). "For example, overexpression of ATAD2 can activate the mitogen-activated protein kinase (MAPK) pathway to promote the proliferation of ovarian cancer cells." (PMID 36632213, 2023). "In ovarian cancer cells, changes in CENPE expression following ATAD2 inhibition resulted in cell-cycle arrest and apoptosis induction, which led to the suppression of ovarian cancer growth." (PMID 37479754, 2023). "Our analysis of several publicly available mRNA expression data sets revealed that ATAD2 is significantly overexpressed in patient-derived ovarian cancer samples as compared to normal ovary tissue samples." (PMID 37479754, 2023). "Our study, for the first time, shows that ATAD2 is a promoter of ovarian cancer tumor growth by regulating CENPE expression." (PMID 37479754, 2023). "Here, we demonstrate that ATAD2 is overexpressed in ovarian cancer, and ATAD2 overexpression predicts metastatic disease progression and disease recurrence in patient-derived ovarian cancer samples." (PMID 37479754, 2023). "Collectively, these results establish that ATAD2 promotes ovarian cancer growth and metastasis in ovarian cancer cells." (PMID 37479754, 2023). "We examined the effects of ATAD2 inhibition on ovarian cancer growth in a cell culture model using both pharmacological and genetic approaches." (PMID 37479754, 2023). "Collectively, these results demonstrate that ATAD2 is overexpressed in ovarian cancer samples at both the mRNA and protein levels and is associated with metastatic progression." (PMID 37479754, 2023).
ovarian carcinoma (continued). "ATAD2 has also been reported to be targeted by miR-200b-5p in ovarian cancer cells, where miR-200b overexpression suppresses proliferation and promotes the apoptosis of ovarian cancer cells by inhibiting ATAD2 expression." (PMID 36139505, 2022). "The resistance of ovarian cancer chemotherapy patients to platinum drugs is a problem that cannot be ignored, which is related to the miR-302/ATAD2 axis." (PMID 36008934, 2022). "Consistent with our results, a recent study has demonstrated that miR-302 attenuates the epithelial–mesenchymal transition and cisplatin resistance by targeting ATAD2 in ovarian cancers." (PMID 36139505, 2022). "Furthermore, we observed that the CENPE inhibitor GSK923295 significantly potentiated the tumor-suppressive effects of the ATAD2 inhibitor BAY-850 in ovarian cancer cells." (PMID 37479754, 2023). "Thus, our study identified ATAD2 as regulators of ovarian cancer growth and metastasis that can be targeted either alone or in combination with CENPE inhibitors for effective ovarian cancer therapy." (PMID 37479754, 2023). "Additionally, analysis of Human Protein Atlas data sets revealed that ATAD2 protein is also overexpressed in the majority of patient-derived ovarian cancer samples, in agreement with the mRNA expression data." (PMID 37479754, 2023). "Furthermore, we show that ATAD2 inhibition suppresses tumor growth and metastasis in both in vitro and in vivo models of ovarian cancer." (PMID 37479754, 2023). "We next examined the mechanism by which ATAD2 promotes ovarian cancer growth." (PMID 37479754, 2023). "Besides, miR-302 increases the cisplatin sensitivity of ovarian cancer cells by inhibiting ATAD2 to hinder the invasiveness and EMT in cisplatin-resistant cells." (PMID 36632213, 2023). "Additionally, our results indicate that CENPE inhibitors can be combined with ATAD2 inhibitors for effective ovarian cancer therapy." (PMID 37479754, 2023). "We next interrogated the mechanism by which ATAD2 expression is upregulated in ovarian cancer." (PMID 37479754, 2023). "We anticipate that the difference in sensitivity could be due to the other factors beyond ATAD2 that could modulate the intrinsic sensitivity of ovarian cancer cells to ATAD2 inhibitors." (PMID 37479754, 2023). "Analysis of patient-derived ovarian cancer samples revealed higher ATAD2 expression in metastatic ovarian cancer samples than in primary-site samples; therefore, we asked whether ATAD2 is necessary for the development of metastatic properties in ovarian cancer." (PMID 37479754, 2023). "We next tested whether the ATAD2 inhibitor BAY-850 can suppress ovarian cancer growth in vivo." (PMID 37479754, 2023). "However, in ovarian cancer, the contributions of ATAD2 to disease progression and the value of therapeutic ATAD2 targeting remain unknown." (PMID 37479754, 2023). "Collectively, our studies illuminate the role of ATAD2 as a facilitator of ovarian cancer growth and metastasis and indicate that ATAD2 inhibitors, used either alone or in combination with CENPE inhibitors, may represent therapeutic option for treating ovarian cancer patients." (PMID 37479754, 2023). "However, in ovarian cancer, the role played by ATAD2 and whether targeting ATAD2 has therapeutic value is not well understood." (PMID 37479754, 2023). "We then asked whether ATAD2 overexpression plays a role in ovarian cancer growth and metastasis." (PMID 37479754, 2023). "Pharmacological CENPE inhibition phenotypically recapitulated the cellular changes induced by ATAD2 inhibition, and combined pharmacological inhibition of both ATAD2 and CENPE inhibited ovarian cancer cell growth more potently than inhibition of either alone." (PMID 37479754, 2023). "Conversely, highly expressed ATAD2 protein can promote the protein expression levels of PI3K and p-Akt to promote ovarian cancer progression." (PMID 36632213, 2023).
ovarian carcinoma (continued). "Collectively, these results demonstrate that ATAD2 inhibition via BAY-850 leads to cell-cycle arrest and apoptosis induction, which, in turn, suppresses ovarian cancer growth and progression." (PMID 37479754, 2023). "ATAD2, a directed target of miR-302, inhibits APC and promotes nuclear β-catenin expression to reduce the sensitivity of ovarian cancer cells to cisplatin and enhance cisplatin-resistant cell migration, invasion, and EMT abilities." (PMID 36008934, 2022). "Analyses of TCGA data suggest similar relationships between ATAD2, 8q24 amplification, and MYC pathway activation in glioblastoma, breast, and ovarian cancers." (PMID 23393560, 2013). "Likewise, ATAD2 inhibition by miR-200b impedes the protein expression levels of PI3K and p-Akt, thereby inhibiting the proliferation and apoptosis of ovarian cancer cells." (PMID 36632213, 2023). "Finally, we demonstrate that the combined use of both ATAD2 and centromere protein E (CENPE) inhibitors results in a more potent suppressive effect on ovarian cancer growth than the use of either inhibitor alone." (PMID 37479754, 2023).
colorectal cancer (11 papers, 2015 to 2025). A primary or metastatic malignant neoplasm that affects the colon or rectum. "Upregulation of ATAD2 has been observed in various solid malignancies, including prostate, ovarial, and colorectal cancer, and was associated with chemoresistant phenotypes." (PMID 40962957, 2025). "Beyond TNBC, ATAD2 deletion in colorectal cancer (CRC) cells reduces expression of cyclin D1, pRb, E2F1, and cyclin E, suggesting that the ATAD2–B-MYB axis is a conserved driver of oncogenic cell cycle control across multiple tumor types." (PMID 41154392, 2025). "Making ATAD2 a novel molecular marker of metastatic colorectal cancer and providing new insights for clinical diagnosis and treatment of colorectal cancer." (PMID 37644393, 2023). "CRNDE directly binds and inhibits the target gene miR-126-5p that negatively regulates the expression of ATAD2, thereby promoting the development of colorectal cancer and paclitaxel resistance." (PMID 36008934, 2022). "(A) T1 colorectal cancer (CRC) samples from a set of 47 cases were used to verify the abundance of ABI1, ITPR2, RHOT2, ATAD2, and ISLR." (PMID 37158593, 2023). "In colorectal cancer, the oncogenic ubiquitin E3 ligase TRIM25 binds and stabilizes ATAD2 expression following genotoxic stress, which induces a positive ATAD2-E2F-TRIM25 feedback loop whereby ATAD2 acts as a transcriptional co-activator of E2Fs to promote TRIM25 expression." (PMID 38596293, 2024).